SLC22A12 (solute carrier family 22 member 12)
Diseases named in the same sentence as SLC22A12 in open-access papers (continued):
Sharing a sentence is not in itself a finding about the gene and the disease.
gout (continued). "Whole-genome sequencing studies further identify novel genetic loci (RCOR1, FSTL5-MIR4454) and transporter variants (ABCG2, SLC22A12) associated with early-onset gout, with RCOR1 promoting NLRP3 inflammasome activation and IL-1β release, which are key drivers of gouty inflammation." (PMID 40880930, 2025). "SLC22A12, also known as urate transporter 1, is involved in regulating urate levels in the blood and its variants are associated with serum uric acid level and gout development." (PMID 36635277, 2023). "In addition, they found that the protective effect of SLC22A12 on gout exceeded the pathogenic effect of ABCG2 on gout." (PMID 35922835, 2022). "Individuals carrying SLC22A12 variants have a lower risk of developing gout." (PMID 35813212, 2022). "Inhibitors of renal uric acid reabsorption through URAT1 (SLC22A12) are commonly used in treating gout, but additional transporters implicated through human genetics may also prove to be useful drug targets." (PMID 34001247, 2021). "However, consistent with the findings of other studies, our data suggest that p.V282I and c.1002+78A>G (SLC2A9) reduce the risk of gout, while p.N82N (SLC22A12) increases the risk." (PMID 32759716, 2020). "However, the authors of another study came to different conclusions; they found nonsynonymous variants of the SLC22A12 gene in 16 patients from a cohort of 69 individuals with gout." (PMID 32759716, 2020). "Among these, ABCG2 and SLC22A12 genes are known risk factors for gout in different populations." (PMID 30621105, 2019). "While the role of genetic variants of ABCG2 and SLC22A12 in the gout pathogenesis has been reported, substantial inconsistencies and certain discrepancies in multiple populations of European and Asian ancestries exist due to the effect of various genes and different genetic backgrounds." (PMID 30621105, 2019). "While several studies have reported the relationship between ABCG2 and SLC22A12 variants and gout in various ethnic populations, to our best knowledge, the current study was the first one to investigate the genotype distributions and effects of these SNPs on the Vietnamese population." (PMID 30621105, 2019). "Interestingly, to our knowledge, our result provides an evidence of the association between SLC22A12 rs11231825 with gout susceptibility in an Asian population." (PMID 30621105, 2019). "In addition to previous reports in different populations, our results provide more evidence on the association of ABCG2 rs72552713 and SLC22A12 rs11231825 with gout and serum uric acid in the Vietnamese population." (PMID 30621105, 2019). "Incorporating genetic screening for SLC22A12 variants into clinical practice may enable more personalized treatment strategies, optimizing the selection of uricosuric drugs and improving outcomes in gout management." (PMID 39409183, 2024). "GWASs and meta-analyses have identified several genes associated with gout susceptibility, including SLC2A9, SLC22A12, and SLC22A11." (PMID 41137353, 2025). "Human genomic studies have identified many urate transporter genes, including ABCG2, SLC22A12, SLC2A9, and OAT4 as risk factors for gout by conducting genome-wide analyses and meta-analyses." (PMID 36139553, 2022). "It is certain that SLC22A13, like SLC22A12, can provide effective targets for the treatment of gout." (PMID 35922835, 2022). "A genomic study analyzed the epistasis of ALPK1 with the loci of GLUT9, ALPK1, SLC22A12, and ABCG2, finding a positive predictive value (PPV ≥ 81%) to measure the risk of gout (OR ≥ 12.30) using variants of these genes in different populations." (PMID 35505381, 2022). "Because genetic variants in urate transporter genes such as ABCG2, SLC2A9 and SLC22A12 are well known to cause SUA variation and gout, it is also possible that the SLC38A1/SNAT1 transporter is involved in urate or purine transport." (PMID 32238385, 2020).
gout (continued). "Recent GWASs of clinically defined gout have revealed associations between gout and urate transporter genes, such as ABCG2/BCRP, URAT1/SLC22A12, GLUT9/SLC2A9, NPT1/SLC17A1, all of which are expressed in the proximal tubular cells of the kidney." (PMID 31975031, 2020). "rs146978188 is also in LD with an SNP of SLC22A15/FLIPT1, an orphan transporter gene in the same family as SLC22A12/URAT1, a well-known urate transporter gene that is strongly associated with gout." (PMID 32238385, 2020). "To understand of the relationship between these genes and gout we conducted a case-control association study of ABCG2 rs72552713, rs12505410 and SLC22A12 rs11231825, rs7932775 in the Vietnamese population." (PMID 30621105, 2019). "In spite of these restrictions, our study was the first to reveal associations between SNPs (rs72552713 in ABCG2, and rs11231825 in SLC22A12) and gout among Vietnamese." (PMID 30621105, 2019). "For example, urate transporter genes ABCG2, SLC2A9, and SLC22A12 modulate the relationship of renal urate homeostasis and gout with T2DM." (PMID 30615649, 2019). "Over the last two decades, genome-wide association studies and meta-analyses have identified several genes associated with gout susceptibility, including ATP-binding cassette subfamily G member 2 (ABCG2) and solute carrier family 22 member 12 (SLC22A12)." (PMID 30621105, 2019). "Risk of gout was halved in carriers of rare variants in SLC22A12, illustrating the therapeutic potential of the new URAT1-blocker lesinurad." (PMID 30315176, 2018). "Many studies have shown significant associations between SNPs in SLC22A12 and SUA levels or/and gout." (PMID 26290326, 2015). "Our analysis provides evidence for multiple ancestral-specific effects across the SLC22A11/SLC22A12 locus that presumably influence the activity of OAT4 and URAT1 and risk of gout." (PMID 24360580, 2013). "There is inconsistent association between urate transporters SLC22A11 (organic anion transporter 4 (OAT4)) and SLC22A12 (urate transporter 1 (URAT1)) and risk of gout." (PMID 24360580, 2013). "Lesinurad, an SLC22A12 inhibitor approved by the FDA for the treatment of gout." (PMID 39850557, 2024). "As expected, many transporter genes such as URAT1/SLC22A12, GLUT9/SLC2A9, ABCG2/BCRP, NPT1/SLC17A1, and OAT10/SLC22A13 were identified as having an association with gout and SU in addition to several enzyme genes, including the ALDH2 gene, which has a pivotal role in alcohol metabolism." (PMID 38137389, 2023). "The SLC22A12 gene is responsible for encoding URAT1, and a mate analysis suggested that the rs 475688 polymorphism in the SLC22A12 gene is associated with susceptibility to gout." (PMID 36203589, 2022). "Not surprisingly, the SLC22A12: p.W258X mutation showed a protective effect against gout incidence in comparison with healthy controls." (PMID 31131560, 2019). "The majority of the rare variants in SLC22A12 were associated with lower serum urate levels, and carriers showed half the risk of gout compared to non-carriers." (PMID 30315176, 2018). "URAT1 (SLC22A12) appears to be one of the major uric acid transporters in the kidney, and mutations and SNPs in it have been associated with altered uric acid levels, gout and kidney stones." (PMID 26536134, 2015). "Therefore, we performed a genetic association study of these SUA loci (PDZK1, GCKR, SLC2A9, LRRC16A, SLC17A1, SLC16A9, SLC22A11 and SLC22A12) in gout patients and normal control volunteers of Han Chinese origin." (PMID 26290326, 2015). "We found significant association of uric acid concentrations with three gout-related SNPs (rs780094 in GCKR, corrected p = 3.94E−5; rs1183201 in SLC17A1, corrected p = 0.005; rs505802 in SLC22A12, corrected p = 0.003) and of triglycerides with rs780094 (located in GCKR, corrected p = 2.96E−4)." (PMID 26290326, 2015).
gout (continued). "The ABCG2, SLC22A12, and ALPK1 genes have been strongly associated with dysfunction of urate metabolism in patients with gout, but it is unknown how these transporters are expressed in patients with acute or chronic gout." (PMID 35505381, 2022). "Another meta-analysis of GWASs on serum urea salt concentrations and gout in African Americans found genome-wide significance at three loci (SLC2A9, solute carrier family 2 member 12 (SLC2A12), and SLC22A12)." (PMID 35813212, 2022). "Genome-wide association studies (GWASs) have explored many genes associated with gout, for instance, ABCG2, PKD2, SLC2A9, KCNQ1, SLC22A12 and SLC17A1 for gout disease among individuals of European descent." (PMID 30899057, 2019). "Among these genes, SLC22A12, CDC42BPG, and SLC2A9 were previously found to be related to serum uric acid levels or gout." (PMID 28410202, 2017). "Because URAT1 is a well-known urate transporter that markedly affects SUA level, these findings indicate that the true associated gene for combined type gout on chromosome 11q13.1 locus is not CDC42BPG, but SLC22A12/URAT1." (PMID 32238385, 2020). "Although functional consequences of SLC22A12 polymorphisms have not been fully characterized, several SLC22A12 variants, including rs475688, rs7932775, rs382507, rs57606, rs7932775 rs11231825 and rs11602903, have been linked to elevated SUA and gout susceptibility." (PMID 30621105, 2019).
renal hypouricemia (47 papers, 2008 to 2025). "Loss-of-function mutations in SLC22A12 lead to renal hypouricemia, a condition characterized by excessive urinary urate excretion and very low serum urate levels." (PMID 40169562, 2025). "Before the characterization of SLC2A9, most of the clinical studies focused on SLC22A12, and over 90% of renal hypouricemia was reported from SLC22A12 mutations." (PMID 38166558, 2024). "A number of genetic mutations can also cause renal hypouricemia, such as mutations in SLC22A12, which encodes URAT1, and SLC2A9, which encodes GLUT9." (PMID 37108190, 2023). "Our findings suggest that these loss-of-function mutations cause renal hypouricemia via loss of UA reabsorption and expand the variation spectrum of the SLC22A12 gene." (PMID 37761963, 2023). "Idiopathic renal hypouricemia can be caused by a mutation of URAT1 (SLC22A12; organic anion/urate transporter)." (PMID 36611832, 2022). "Renal hypouricemia (RHUC) is a hereditary disorder where mutations in SLC22A12 gene and SLC2A9 gene cause RHUC type 1 (RHUC1) and RHUC type 2 (RHUC2), respectively." (PMID 32375679, 2020). "Renal hypouricemia (RHUC) is a genetic disorder caused by mutations in the SLC22A12 gene, which encodes the major uric acid (UA) transporter, URAT1." (PMID 32677916, 2020). "Mutations in the SLC22A12 gene were identified in patients with renal hypouricemia, causing reduced uric acid levels in the blood." (PMID 30621105, 2019). "Mutations in SLC22A12 or SLC2A9 were initially reported in Japanese patients with renal hypouricemia, although patients from various ethnic groups have subsequently been identified." (PMID 30189835, 2018). "A Japanese study showed that patients with renal hypouricemia caused by the mutation of SLC22A12 were among those with low but more than 2 mg/dl serum uric acid levels." (PMID 25658588, 2015). "The regulation of urate excretion, especially by a cluster of urate transporters in the kidneys, is important in the homeostasis of SUA, which has been corroborated by the presence of type I and type II renal hypouricemia caused by SLC22A12 and SLC2A9 dysfunction, respectively." (PMID 38397902, 2024). "Renal hypouricemia is currently classified into two types according to its causative genes—genetic dysfunction in urate transporter 1 (URAT1, also known as SLC22A12) and glucose transporter 9 (GLUT9, also known as SLC2A9) corresponds to RHUC type 1 and RHUC type 2, respectively." (PMID 36733941, 2022). "Herein, we report a nine year old Sri Lankan boy with renal hypouricemia (serum uric acid 97 μmol/L, fractional excretion of uric acid 33%).The sequencing analysis of SLC22A12 revealed a potentially deleterious missense variant c.1400C > T (p.T467 M, rs200104135) in heterozygous state." (PMID 29958533, 2018). "Mutations in the SLC22A12 gene are responsible for most cases of renal hypouricemia." (PMID 28877755, 2017). "Mutations in SLC22A12 are thought to be the major cause of idiopathic renal hypouricemia in humans, which is also called “Dalmatian hypouricemia” since people with this disorder spill uric acid into their urine resulting in a phenotype similar to the Dalmatian dogs." (PMID 18989453, 2008). "Significant alterations of SLC2A9 could cause primary renal hypouricemia in people similar to SLC22A12 mutations since genetic heterogeneity exists for this disorder." (PMID 18989453, 2008). "Interestingly, a recent observation added new evidence of UA as antioxidant acting to protect the endothelial function, as patients with renal hypouricemia (<2.5 mg/dL due to SLC22A12/URAT1 loss-of-function mutations) present a marked reduction of flow-mediated dilation." (PMID 28933392, 2016). "We focused on urate transporters in the kidney, particularly URAT1/SLC22A12, a urate anion exchanger regulating serum uric acid levels, and described uricosuric agents and patients with renal hypouricemia who have mutational defects in SLC22A12." (PMID 35327453, 2022).
renal hypouricemia (continued). "Hypouricemia caused by a renal tubular defect has been termed “renal hypouricemia”, and loss-of-function mutations of the SLC22A12 and SLC2A9 genes are called type 1 and type 2 renal hypouricemia, respectively." (PMID 36431026, 2022). "hURAT1(Slc22a12) is a transporter responsible for renal urate reabsorption; renal hypouricemia will occur in patients with abnormalities in the hURAT1 gene." (PMID 35447931, 2022). "Renal hypouricemia (RHUC) is caused by an inherited defect in the main reabsorption system of uric acid, SLC22A12 (URAT1) and SLC2A9 (GLUT9)." (PMID 34829836, 2021). "The loss of function mutations in SLC22A12 and SLC2A9 causes renal hypouricemia (RHUC) type 1 and type 2, respectively." (PMID 32375679, 2020). "Renal hypouricemia (RHUC) is caused mainly by urate transporter gene mutations, including SLC22A12 (URAT1) and SLC2A9 (GLUT9/URATv1)." (PMID 30836687, 2019). "In addition to LOF in SLC22A12, mutations in SLC2A9, which encodes GLUT9, cause renal hypouricemia (renal hypouricemia type 2), indicating its importance in human urate metabolism." (PMID 40100301, 2025). "Renal hypouricemia is believed to arise owing to genetic defects in SLC22A12 and SLC2A9; this is based on the “rare disease, rare variant hypothesis”38." (PMID 32514006, 2020). "Different loss-of-function mutations or variants in the SLC22A12 gene have been identified in patients with renal hypouricemia (lack of serum uric acid)." (PMID 30621105, 2019). "Moreover, we previously published the high frequencies for the common dysfunction allelic variants c.1245_1253del and c.1400C > T of SLC22A12 (renal hypouricemia type 1, OMIM 220150) among the Roma, and those prevalent variants were also identified in Roma Spanish patients with renal hypouricemia." (PMID 40707723, 2025). "Renal hypouricemia (RHUC) is a rare hereditary disorder caused by loss-of-function mutations in the SLC22A12 (RHUC type 1) or SLC2A9 (RHUC type 2) genes, encoding urate transporters URAT1 and GLUT9, respectively, that reabsorb urate in the renal proximal tubule." (PMID 37761963, 2023).
Insulin resistance (27 papers, 2016 to 2026). Increased resistance towards insulin, that is, diminished effectiveness of insulin in reducing blood glucose levels. "Thus, our study demonstrates a previously unrecognized SLC22A12 genotype-specific effect on serum urate levels in association with insulin resistance and hyperinsulinemia using a large-scale biomedical database from the UKBB." (PMID 40100301, 2025). "Mechanistically, elevated insulin resistance ameliorates renal UA excretion by stimulating UA-anion exchanger UA transporter 1 (URAT1, as SLC22A12)." (PMID 35885024, 2022).
acute kidney injury (14 papers, 2011 to 2025). Sudden and sustained deterioration of the kidney function characterized by decreased glomerular filtration rate, increased serum creatinine or oliguria. "Hereditary renal hypouricaemia type 1 is due to loss of function mutations in URAT1 (SLC22A12) and is relatively common in Japan, and can be complicated by nephrolithiasis or exercise-induced acute renal failure." (PMID 23895142, 2013).
metabolic syndrome (14 papers, 2013 to 2025). A cluster of metabolic risk factors for CARDIOVASCULAR DISEASES and TYPE 2 DIABETES MELLITUS. "In humans, the presence of single nucleotide polymorphisms (SNPs) in the SLC22A12 gene was found to be associated with obesity and metabolic syndrome in Caucasians with hypertension." (PMID 24433282, 2014).
nephrolithiasis (14 papers, 2011 to 2024). The presence of a calculus in the pelvis of the kidney; this is most often composed of mineral salts and proteins. "Some of these variants in SLC22A12 were discovered following significant clinical episodes including nephrolithiasis in patients SK-1, NC-1 and NC-2." (PMID 22194875, 2011). "We now report a case of RHUC complicated with an asymptomatic kidney stone, and we identified a heterozygous mutation of c.269G > A (p.R90H) and a novel heterozygous mutation of c.674C > G (p.T225R) in the SLC22A12 gene in the patient through whole exon gene detection (NGS method)." (PMID 38384421, 2024). "Additional factors, such as sequence variation in other UA transporters (SLC22A12, SLC17A3, ABCC4 and ABCG2), age, sex, diet, drugs, physical activity, environment and volume status can influence the degree of UA tubular absorption and the risk of EIARF or nephrolithiasis." (PMID 24397858, 2014). "However, nephrolithiasis and exercise induced renal failure (EIRF) have been reported in individuals with mutations in either the SLC22A12 (URAT1) or SLC2A9 (GLUT9) but not XDH (XO) genes." (PMID 29904633, 2018).
Hyperinsulinemia (10 papers, 2020 to 2025). An increased concentration of insulin in the blood. "We found that SLC22A12 expression quantitative trait locus (eQTL) rs475688 synergistically enhanced the positive association between serum urate and hyperinsulinemia." (PMID 40100301, 2025). "Thus, in contrast to rs475688, rs147647315 within SLC22A12 tended to synergistically diminish the effects of hyperinsulinemia on serum urate levels." (PMID 40100301, 2025).
renal hypouricemia type 2 (5 papers, 2020 to 2025). "Currently, only two urate transporters related to the Mendelian disorders have been reported: SLC22A12 (OMIM 220150), which is responsible for renal hypouricemia type 1 (RHUC1), and SLC2A9 (OMIM612076) which is responsible for renal hypouricemia type 2 (RHUC2)." (PMID 38166558, 2024).
hereditary renal hypouricemia (3 papers, 2019 to 2023). Hereditary renal hypouricemia (HRH) is a rare autosomal recessively inherited renal membrane transport disorder affecting urate reabsorption in the proximal tubules leading to usually asymptomatic hypouricemia and predisposing to urolithiasis and exercise induced acute renal failure (EIARF). "A SLC22A12 p.W258* variant was first found in a Japanese patient with idiopathic renal hypouricemia and exercise-induced acute renal failure, and has been reported further in Korean and Japanese patients with hereditary renal hypouricemia." (PMID 32271837, 2020).
COVID-19 (2 papers, 2021 to 2024). A disease caused by infection with severe acute respiratory syndrome coronavirus 2. "Based on these observations and on the defective tubular handling of uric acid, we investigated the expression of urate transporter URAT1 (SLC22A12), which mediates the reabsorption of uric acid at the apical membrane of proximal tubule cells in kidneys from COVID-19 patients." (PMID 34127048, 2021).